SOX9 (SRY-box transcription factor 9)
Diseases named in the same sentence as SOX9 in open-access papers (continued):
Sharing a sentence is not in itself a finding about the gene and the disease.
hepatocellular carcinoma (72 papers, 2012 to 2025). A malignant tumor that arises from hepatocytes. "The transfection of human hepatoma cells with the mutant bovine allele reduced the ability of PRKG2 to inhibit SOX9-mediated downregulation of the collagen type II expression." (PMID 34680883, 2021). "These cells express the CCA markers SRY (Sex Determining Region Y)-Box 9 (SOX9), cytokeratin (CK)-7 and 19 but lack hepatocyte nuclear factor 4 alpha and alpha-smooth muscle actin, markers of hepatocellular carcinoma and cancer-associated fibroblasts, respectively." (PMID 29464042, 2018). "This is also the case in the context of liver cancer; Sox9 expression in hepatocellular carcinoma (HCC) cells was associated with a more undifferentiated state, venous invasion, and reduced overall survival in patients." (PMID 30992706, 2019). "Knockdown of circRNA ZNF292 (cZNF292) increased SOX9 nuclear translocation, subsequently reduced Wnt/β‐catenin pathway activity, leading to suppression of VM in hypoxic hepatoma cell." (PMID 39964093, 2025). "SRY (through its downstream factor SOX9) impairs the differentiation of liver progenitor cells into hepatocytes, contributing to chronic liver inflammation and fibrosis, thereby promoting hepatocellular carcinoma (HCC) progression." (PMID 40438106, 2025). "In hepatocellular carcinoma, SOX9 is essential for the self-renewal and proliferation of liver cancer stem cells, which contribute to tumor progression and drug resistance." (PMID 40428248, 2025). "SOX9-expressing hepatocellular carcinoma (HCC) cells exhibit CSC-like characteristics, including bipotent differentiation, self-renewal, high proliferation, colony and sphere formation and resistance to 5-fluorouracil." (PMID 40374599, 2025). "It has been shown to reduce hepatocellular carcinoma cell proliferation by targeting SOX9 and to suppress lung adenocarcinoma cell tumorigenesis in vivo by binding to PRC1." (PMID 39684278, 2024). "In hepatocellular carcinoma, compared to normal adherent growing tumor cells, the sphere model system exhibits a significant enrichment of Sox9." (PMID 38978960, 2024). "circRNA circHipk2 expression in C2C12 myoblasts is mediated by Sp1, and circ-FOXP1 in hepatocellular carcinoma cells is regulated by SOX9." (PMID 35832649, 2022). "In summary, this study reveals the role of Notch in hepatocyte dedifferentiation through downregulation of Sox9 in krasG12V-induced hepatocellular carcinoma, providing a potential target for clinical studies of HCC." (PMID 35563098, 2022). "SOX9, which can be directly induced in HBV-infected human hepatoma cells has been identified as a risk factor for cirrhosis and HCC." (PMID 36569318, 2022). "Previous studies have found that high Sox9 expression in hepatocellular carcinoma promotes stemness and tumorigenesis in liver cancer stem cells and is also associated with poor survival rates in patients with liver cancer." (PMID 35563098, 2022). "Armcx3 was also found to promote hepatic cell proliferation through the interaction with Sox9, a known proliferation factor in hepatocellular carcinoma." (PMID 33807672, 2021). "Study has identified that SOX9 is a proliferation and stem cell factor in hepatocellular carcinoma, and it has the same role in OC." (PMID 34881182, 2021). "We found, using co-immunoprecipitation assays, that ARMCX3 and SOX9 physically interact in hepatoma cells." (PMID 33807672, 2021). "Here, we demonstrate that DCLK1-overexpressing hepatoma cells develop into spheroids composed of SOX9 + and α-fetoprotein + cells." (PMID 32601309, 2020). "A recent study found that the transcription factor SOX9 can significantly upregulate the expression of hepatocellular carcinoma circFoxp121." (PMID 32951006, 2020). "For example, miR-138 targets SP1 regulated cell proliferation in hepatocellular carcinoma; SOX9 was targeted by miR-138 to regulated cell invasion in renal cell carcinoma." (PMID 31096819, 2019).
hepatocellular carcinoma (continued). "SOX9, one target of miR-145, has been reported up-regulated in many carcinomas and has been regarded to be an important oncogene which promotes migration found that SOX9 functioned as a tumor promotion in hepatocellular carcinoma partially induced by miR-138." (PMID 30285605, 2018). "In hepatocellular carcinoma, Sox9 activates the canonical Wnt pathway through direct binding with Fzd7." (PMID 28279198, 2017). "Hepatocellular carcinoma with SOX9 positivity in a majority of tumour cells (more than 50% of tumour cells) displayed a nearly uniform expression throughout the tumour." (PMID 29121666, 2017). "In this study, we investigated the role of Sox9 and its molecular mechanism with reference to stemness properties in hepatocellular carcinoma (HCC)." (PMID 27105493, 2016). "In hepatocellular carcinoma (HCC), a recent study showed that Sox9 overexpression is associated with higher tumor stage and tumor grade and poorer survival." (PMID 27105493, 2016). "Both miR-145 and miR-495 target SOX9 in mesenchymal stem cells, and miR-101 targets SOX9 in hepatocellular carcinoma." (PMID 27261459, 2016). "Additionally, SRY, via its downstream target SOX9, promotes hepatocellular carcinoma (HCC) progression by upregulating CXCL5 expression and activating the CXCL5/CXCR2 signaling axis, thereby enhancing tumor cell proliferation and invasion." (PMID 40438106, 2025). "These promising results confirmed the relationship between SOX9 expression status and medical imaging and further indicated that our DL model is a promising approach for identifying SOX9 status and holds significant potential for guiding precision treatment strategies in hepatocellular carcinoma." (PMID 40428248, 2025). "To date, several studies have reported various roles of miR-206, such as regulating the growth and migration of hepatocellular carcinoma cells by affecting Sox9, participating in the injury of endothelial cells, and certain early diagnostic significance for skeletal muscle injury." (PMID 38446322, 2025). "In this retrospective study, we developed and validated a reinforcement learning (RL)-based deep learning (DL) model that can non-invasively identify the SOX9 status of hepatocellular carcinoma (HCC) patients preoperatively, providing support for personalized treatment." (PMID 40428248, 2025). "Moreover, examination of CD44v6 and SOX9 expression by IF on human liver carcinoma sections revealed a high density of CD44v6+ and SOX9+ cells." (PMID 41168417, 2025). "However, recent studies using Sox9 chromatin immunoprecipitation (ChIP) combined with deep sequencing (ChIP-seq) analysis have reported that Sox9 can activate canonical Wnt/β-catenin signaling in hepatocellular carcinoma and prostate cancer." (PMID 28279198, 2017). "SOX9 has been previously shown to be involved in hepatocellular carcinoma (HCC) and other types of cancer." (PMID 29121666, 2017). "Furthermore, miR-101 can control SOX9 expression levels in hepatocellular carcinoma." (PMID 26853752, 2016). "Previous studies have established that SOX9 is a significant biological marker of recurrence-free survival (RFS) and poor prognosis in hepatocellular carcinoma (HCC)." (PMID 40428248, 2025). "Conversely, SOX9 inhibits the replication of HBV in human hepatoma cells by binding to and blocking HBV Enhll/Cp via HMG domain of SOX9 gene." (PMID 39974732, 2025). "To determine the effect of SOX9 on YAP-driven malignancy, we infected hepatocellular carcinoma (HCC) cells with lenti-YAP." (PMID 38653754, 2024).
hepatocellular carcinoma (continued). "For example, the expression of the circular RNA circ-FOXP1 was remarkably upregulated in hepatocellular carcinoma (HCC) tissues, and this upregulated circFOXP1 was induced by SOX9, which promoted HCC progression through sponging to miR-875-3p and miR-42124." (PMID 38745044, 2024). "SOX9 trans-activated long non-coding RNA NEAT1, which stimulates self-regeneration of hepatocellular carcinoma stem cells via the PKA/Hippo pathway." (PMID 37183261, 2023). "Bioinformatics prediction and dual luciferase reporter gene assays proved that SOX9 and TPM4 were the target genes of miR-5195-3p in hepatoma cells." (PMID 37328795, 2023). "In hepatocellular carcinoma (HCC) CD73 was shown to contribute to resistance to Lenvatinib, a VEGF inhibitor, through AKT overactivity which resulted in increased SOX9 expression and stemness of HCC cells." (PMID 37033953, 2023). "SPP1 is a downstream target of SOX9 which results in elevated serum SPP1 levels and SPP1 can serve as a useful surrogate marker of SOX9 in hepatocellular carcinoma." (PMID 36182943, 2022). "In addition, Sox9 is highly expressed in hepatocellular carcinoma (HCC) tissues, which promotes the self-renewal of HCC stem cells and affects the occurrence and differentiation of HCC." (PMID 34505013, 2021). "Moreover, aaptamine 16 displayed a potent anticancer effect in mice carrying human hepatocellular carcinoma HCC-LM3 xenografts with downregulation of SOX9 and Ki67 expression." (PMID 34299599, 2021). "Spheroids derived from DCLK1-overexpressing hepatoma cells showed high level expression of active β-catenin, α-fetoprotein, and SOX9, suggesting that DCLK1 overexpression induces clonogenicity and dedifferentiated phenotypes in hepatoma cells." (PMID 32601309, 2020). "miR-105 was reported to serve as tumor-suppressive miRNAs in glioma by targeting SOX9 and SUZ12, as well as in hepatocellular carcinoma by targeting NCOA1." (PMID 29258605, 2017). "It is noteworthy that a study illustrated that miR-101 directly targets SOX9 in human hepatocellular carcinoma (HCC), and miR-101 could suppress SOX9-dependent tumorigenicity and promotes favorable prognosis of HCC." (PMID 27911279, 2017). "Further investigation showed that cZNF292 knockdown inhibited hepatoma vasculogenic mimicry (VM) and radioresistance in vitro and in vivo by increasing sex-determining region Y (SRY)-box 9 (SOX9) nuclear translocation, subsequently reducing Wnt/β-catenin signalling pathway activity." (PMID 31973726, 2020). "However, the clinical significance of SOX9 expression in hepatocellular carcinoma (HCC) remains unclear." (PMID 22515642, 2012). "Lineage tracing experiments show that Sox9+ hepatocyte is a sub-population of periportal hepatocytes, after chronic hepatocyte failure, this sub-population will experience extensive proliferation to replenish liver mass, which will not develop into hepatocellular carcinoma." (PMID 37649095, 2023). "SOX8 and SOX9 induced the FZD7-mediated activation of the WNT/β-catenin pathway to regulate chemoresistance, stem-like properties and EMT in tongue squamous cell carcinoma (TSCC) and hepatocellular carcinoma (HCC)." (PMID 29789460, 2018). "Therefore, cell lines with elevated SOX9 expression such as the liver carcinoma cell lines HepG2 may not contain palindromic SOX dimer elements within their DHS because SOX9 utilizes a different motif configuration to engage the chromatin in those cells." (PMID 26013289, 2015). "Also, it was shown that SOX9 + cells derived from human hepatocellular carcinoma (HCC) were highly proliferative and able to self-renewal which makes them an appropriate CSC marker in HCC." (PMID 33736633, 2021).
lung carcinoma (70 papers, 2011 to 2025). "While the mutational status of KEAP1 is one of the most critical biomarkers for molecular classification and general survival time of the patients, high SOX9 expression appeared to confer poor outcome in KEAP1‐mutated lung cancer patients." (PMID 33173725, 2020). "By analyzing the clinical datasets, we found that KEAP1 mutations showed significant positive correlation with SOX9 expression in the TCGA lung cancer cohort." (PMID 33173725, 2020). "Taken together, these data suggest that a subset of the KEAP1 mutations leads to elevate SOX9 protein level, which is associated with lung cancer progression." (PMID 33173725, 2020). "Survival analysis by TCGA data showed that high expression of SOX9 was significantly associated with the reduced survival rate in lung cancer patients." (PMID 32686598, 2020). "It was reported recently that SOX9 participates in the feedback loop of MALAT1 (metastasis associated lung adenocarcinoma transcript 1)-miR-101-SOX9, which modulates the chemoresistance of lung cancer cells to Cisplatin via the Wnt signaling pathway." (PMID 31060551, 2019). "While future studies will be required to assess biological significance of these phosphorylation sites in vivo, a similar shift in protein stability for another SOXE family member, SOX9, has been implicated in lung cancer metastasis." (PMID 29315345, 2018). "Sox9 overexpression has been observed in more than 50% of lung adenocarcinomas (ADCs), the most common histological subtype of lung cancer, and is associated with a poor survival in lung ADC patients." (PMID 29245941, 2017). "Capaccione and colleagues found that SOX9 participates in Notch-1–induced lung cancer cell motility, cell invasion, and loss of E-cadherin expression." (PMID 26384302, 2015). "Overexpression of Sox9 is found in more than 50% of lung adenocarcinomas (ADCs), the most common histological lung cancer subtype, and is associated with a poor lung ADC survival." (PMID 25004243, 2014). "Furthermore, KEAP1 mutations showed significant positive correlation with SOX9 expression in the TCGA lung cancer cohort." (PMID 33173725, 2020). "Although several lines of evidence have suggested that SOX9 might be involved in cancer development and progression, only a few studies have linked SOX9 to lung cancer." (PMID 22385677, 2012). "The data revealed that SOX9 could be a lung cancer-associated molecule with a prognostic value." (PMID 22385677, 2012). "The expression of SOX2 and SOX9 is mutually exclusive and is regulated under epigenetic control, influencing tumor growth and invasion in lung cancer." (PMID 39372390, 2024). "This leads to a decrease in apoptosis and increase in cell proliferation, emphasizing the importance of the SOX9/WNT pathway in lung cancer." (PMID 38473318, 2024). "It regulates the expression of the oncogene human pituitary tumor transforming gene-1 (PTTG1) by phosphorylating the transcription factor SOX9, which enhances the migration and invasion of lung cancer cells." (PMID 37835536, 2023). "Nonetheless, it is highly expressed in the human lung and was reported to inhibit lung cancer proliferation and invasion by reducing Wnt signaling through the suppression of SOX9 and β-catenin signaling pathways." (PMID 37932771, 2023). "The expression level of SOX9 was proved again to be closely related to the migration and invasion level of lung cancer cells (A549 cells) in this article." (PMID 37919693, 2023). "The SNHG1/miR-101-3p/SOX9/Wnt/β-catenin axis promotes the progression of non–small cell lung cancer." (PMID 40636922, 2023). "In lung cancer, highly expressed SOX9 promoted cell proliferation and inhibited apoptosis by activating Wnt/β-catenin signaling through phosphorylation of GSK3β." (PMID 35281088, 2022). "In lung cancer, miR-133b is significantly decreased, and it acts as a tumor repressor to inhibit lung cancer development by inhibiting the SRY-box transcription factor 9 (SOX9)/b-catenin signaling pathway." (PMID 35048795, 2022).
lung carcinoma (continued). "In lung cancer, SOX9 promotes cancer cells resistant to cisplatin by increasing aldehyde dehydrogenase (ALDH) activity via ALDH1A1." (PMID 34899911, 2021). "Elevated expression of SOX9 drives EMT in lung cancer through Wnt/β-catenin pathway to promote migration and invasion." (PMID 33632299, 2021). "Previous studies have shown that knockdown of SOX9 in human lung carcinoma cells induces apoptosis via decreased p‐Wnt and β‐catenin expression and that β‐catenin is a pivotal target for glioma and ovarian cancer therapy." (PMID 33841802, 2021). "The data showed that SOX9 expression was upregulated in both radiated tissue and lung cancer tissue." (PMID 34215344, 2021). "Collectively, these data suggest that CUL3 plays a critical role in decreasing SOX9 protein abundance, which is associated with HCC and lung carcinoma progression." (PMID 33173725, 2020). "This work reports that the Cullin 3KEAP1 E3 ubiquitin ligase plays a critical tumor‐suppressive role in lung cancer and liver cancer by negatively controlling SOX9 stability." (PMID 33173725, 2020). "The overexpression of SOX9 activated Wnt/β-catenin signaling and SOX9-Wnt/β-catenin axis regulated apoptosis of human lung cancer cells." (PMID 31027362, 2019). "The regulation of SOX9 on the Wnt/β‐catenin pathway has been reported in several cancers such as lung cancer and HCC." (PMID 31402556, 2019). "SOX9 affects the expression of the cell cycle regulators p21 and cyclin-dependent kinase 4 and thus contributes to an increase in lung cancer growth potential." (PMID 31379926, 2019). "For example, SOX9 knockout was found to decrease lung cancer tumorigenesis, whereas exogenous SOX9 overexpression enhanced tumor volume in mice." (PMID 31060551, 2019). "Upregulation of SOX9 has been reported to regulate growth and promote the proliferation, invasion, and migration of tumor cells in lung cancer in vitro." (PMID 29587675, 2018). "TGF-β secreted by TAMs induces EMT and acquisition of cancer stem cells characteristics in an in vitro model of HCC; in lung cancer TAM-secreted TGF-β induces EMT in lung cancer cells by upregulating SOX9 expression via the c-Jun/Smad3 pathway." (PMID 29701666, 2018). "To determine if SOX9 expression is correlated with number of TAMs, we analyzed the distribution of TAMs (CD163+ macrophages) and SOX9 in specimens from lung cancer patients using immunofluorescent staining." (PMID 29245941, 2017). "In the present study, we demonstrated the interaction between MALAT1 and miR-101, between miR-101 and SOX9, a direct downstream target of miR-101, in lung cancer cells through RNA immunoprecipitation and Luciferase assays." (PMID 29212230, 2017). "Here, evaluation of 164 patients with lung cancer revealed that number of TAMs was positively correlated with SOX9 expression in lung cancer." (PMID 29245941, 2017). "In summary, we demonstrated that MALAT1 plays an important role in the chemo-resistance of lung cancer by functioning as a ceRNA to regulate the expression of SOX9 by inhibiting miR-101 through the downstream Wnt signaling." (PMID 29212230, 2017). "Taken together, these results indicate that SOX9 plays a key role in macrophage-mediated induction of EMT-like phenotype in lung cancer cells." (PMID 29245941, 2017). "Immunohistochemistry revealed that CD163 and SOX9 expression were positively correlated in specimens from 164 lung cancer patients." (PMID 29245941, 2017). "Here, we further investigated the interaction between MALAT1 and miR-101, miR-101 and SOX9 in lung cancer cells using RNA immunoprecipitation assays with the AGO2 antibody." (PMID 29212230, 2017). "As shown in, density of TAMs was positively correlated with SOX9+ staining in lung cancer cells In addition, TAMs secreted TGF-β." (PMID 29245941, 2017). "Subsequently, enhanced MALAT1 expression promotes SOX9 expression, so as to enhance the chemo-resistance of lung cancer cell to DDP." (PMID 29212230, 2017).